MYC (MYC proto-oncogene, bHLH transcription factor)
Diseases named in the same sentence as MYC in open-access papers (continued):
Sharing a sentence is not in itself a finding about the gene and the disease.
angiosarcoma (continued). "The good correlation between MYC and γH2AX in hemangiosarcomas suggested that some pervasive MYC-related process might be stressing the genome throughout the tumor cell population, not just in sporadic cells." (PMID 40970130, 2025). "Notably, studies have reported high-level amplification at the 8q24.21 chromosomal locus and significant MYC overexpression in secondary cutaneous angiosarcomas." (PMID 38826780, 2024). "Furthermore, our CNA analysis identified significant genomic regions linked to hemangiosarcoma pathogenesis, such as alterations in CDKN2A/B, VEGFA, KDR, MYC, and KIT." (PMID 39872607, 2024). "MYC gene amplification was confirmed to play key roles in secondary angiosarcomas." (PMID 33509230, 2021). "The pathogenesis of angiosarcoma is probably also related to other genes, including CIC gene rearrangement, increased expression of the MYC gene and FLT-4 gene, and mutations of PTPRB and PLCG1, but the present study focused on the PD-1/PD-L1 and PI3K/mTOR signaling pathways." (PMID 34397726, 2021). "We also report the current understanding of the molecular pathways involved in angiosarcoma pathogenesis including MYC amplification, activation of angiogenic pathways and different molecular alterations that are associated with angiosarcomas of different aetiology." (PMID 33182685, 2020). "Besides of secondary angiosarcoma, MYC amplification has also been reported in malignant fibrous histiocytoma, high grade chondrosarcoma, epitheloid sarcoma of the proximal type, and in high grade myxoid liposarcomas." (PMID 29765529, 2018). "Furthermore, sun exposure does not seem to lead to the same genetic alterations that are known from radiation induced angiosarcoma, in which MYC amplification was present in 55% of the cases." (PMID 29765529, 2018). "MYC gene amplifications are commonly found in radiation-induced angiosarcomas." (PMID 29731980, 2018). "Amplification of MYC has been shown to be an important marker of radiation-associated angiosarcoma while it is not common in sporadic angiosarcomas." (PMID 29515789, 2018). "Moreover, Fms Related Tyrosine Kinase 4 (FLT4) and MYC co-amplification was observed in 25% of secondary angiosarcomas." (PMID 28056866, 2017). "We therefore report the MYC gene status in a case of angiosarcoma arising at an AVG site." (PMID 26682080, 2015). "Also, upregulation of miR-17-92 decreased thrombospondin-1 (THBS1) expression that enhanced angiogenesis, indicating a MYC-miR-17-92 dependent pathogenesis in the MYC-amplified hemangiosarcoma tumor tissues." (PMID 26137468, 2015). "By comparing the miRNA profile of MYC-amplified and MYC-unamplified angiosarcomas using deep sequencing of small RNA libraries, they identified that the miR-17-92 cluster is preferentially overexpressed in MYC-amplified angiosarcoma." (PMID 25165708, 2014). "Taken together, these data indicate that MYC amplification is enhanced in radiation induced angiosarcomas, but may be an important mediator of primary angiosarcomas as well." (PMID 25374893, 2013). "What are the effects of MYC amplification in angiosarcomas ?" (PMID 25374893, 2013). "Immunostaining for c-MYC has been developed and might help to distinguish angiosarcoma from atypical vascular proliferation in difficult cases." (PMID 24078891, 2013). "The octoploidy neatly compensating MYC-dose between MYC+/− versus MYC-WT hemangiosarcomas could result from either selective pressure on tumor cells to exceed an oncogenic threshold or from endoreduplication somehow provoked by reduced MYC levels, but unrelated to any neoplastic impulse." (PMID 40970130, 2025).
angiosarcoma (continued). "Moreover, MYC amplification may help genetically distinguish radiation-associated angiosarcomas from other RAS subtypes and from sporadic angiosarcomas, both of which demonstrate MYC amplification with substantially lesser frequency." (PMID 38791996, 2024). "The significant upregulation of the miR-17-92 cluster in MYC-amplified angiosarcomas could potentially serve as a biomarker to identify patients with a more aggressive form of the disease, aiding in the stratification of patients and the tailoring of therapeutic strategies." (PMID 39594601, 2024). "However, there is a small subset of primary angiosarcomas harboring also MYC amplification." (PMID 35456944, 2022). "Therefore, the miR-17-92 cluster could be therapeutically targeted to lessen angiogenetic tumour growth in MYC-positive angiosarcomas." (PMID 28895916, 2017). "Interestingly, members of the miR17-92 cluster target THBS1 directly, demonstrating one mechanism by which MYC amplification may induce an aberrant angiogenic phenotype in angiosarcomas." (PMID 25374893, 2013). "The incidence of MYC amplification, detected by FISH, in radiation- or lymphedema-induced angiosarcomas, ranges between 54% and 100% of studied cases." (PMID 35456944, 2022). "High-level gene amplifications of c-MYC were found in 55% (18/33 cases) of secondary angiosarcoma, including secondary angiosarcoma associated with chronic noncongenital lymphedema (number of cases not specified) and not in the patients with primary angiosarcoma (0/28 cases)." (PMID 24078891, 2013). "In cases of secondary angiosarcoma, FLT4 amplification typically co-occurs with MYC." (PMID 41301029, 2025). "MYC amplification at the 8q24.21 locus is a finding that can help define secondary angiosarcomas, as it is not seen in primary tumors." (PMID 39734593, 2024). "MYC high-level gene amplifications were observed in all secondary angiosarcoma cases but not in primary ones, suggesting that, despite their identical morphology, secondary angiosarcomas are genetically different from primary ones." (PMID 39202050, 2024). "RAS had more frequent MYC, FLT4, CRKL, HRAS, and KMT2D alterations than sporadic angiosarcomas." (PMID 38256700, 2024). "This heterogeneity in clinical behaviour might be related to the high genetic variability described in angiosarcomas, with several genes abnormalities identified in B-AS patients such as CIC, PLCG1, KDR and MYC." (PMID 32616718, 2020). "The amplification of MYC did not have an impact on tumor cell morphology, a fact already known from angiosarcoma where MYC amplification did not correlate with the histological grade or other morphologic features." (PMID 29765529, 2018). "Recent findings from our own institute revealed that amplification of MYC (alias c-Myc) occurs in radiation-induced (secondary) angiosarcoma, but not in primary angiosarcoma." (PMID 29765529, 2018). "There is only one study that demonstrates upregulation of miR-17-92 cluster in MYC-amplified hemangiosarcoma compared to hemangiosarcoma with no MYC amplification." (PMID 26137468, 2015). "Among reported cases, none has described high-level MYC gene amplification, a genetic aberration that is increasingly unifying the various clinicopathologic subdivisions of angiosarcoma." (PMID 26682080, 2015). "This is in contrast to primary angiosarcomas, which tend to be present deep in soft tissue and do not have high MYC gene amplification." (PMID 25574331, 2014). "Analysis of 28 primary and 33 secondary angiosarcomas revealed that MYC amplification on chromosome 8q24.21 was found exclusively in 55% of angiosarcomas secondary to radiation or chronic lymphedema, but not in primary angiosarcomas." (PMID 25374893, 2013). "We investigated c-MYC amplification, known to demonstrate a high level of amplification in secondary angiosarcoma (secondary to irradiation or chronic lymphedema) but not in primary angiosarcoma." (PMID 24078891, 2013).
angiosarcoma (continued). "In two other studies, the authors demonstrated that MYC amplification occurred in 100% of secondary angiosarcomas, but was absent in all cases of atypical vascular lesions." (PMID 25374893, 2013). "AVL is negative for MYC, whereas postirradiation angiosarcoma shows strong positive nuclear staining for MYC." (PMID 23050180, 2012). "MYC immunostain is helpful to differentiate between AVL and angiosarcoma." (PMID 23050180, 2012). "Interestingly, although PI3K mutations are seen in primary breast angiosarcomas and MYC mutations are often seen in radiation-associated angiosarcomas, in our study, PI3K and MYC mutations did not exhibit statistically significant mutual exclusivity." (PMID 41301029, 2025). "Our findings align with previous observations in angiosarcomas, where tumors exhibiting greater immune activity—i.e., a ‘hot’ microenvironment—particularly those lacking MYC amplification or located in the head and neck region, were associated with more favorable outcomes." (PMID 40805246, 2025). "Although EHE expresses similar molecular markers to angiosarcoma (CD31, CD34, and ERG), angiosarcoma differs greatly from EHE in terms of light microscopy morphology and often exhibits MYC amplification without CAMTA1/TFE3 expression." (PMID 40896782, 2025). "Further research on MYC in secondary angiosarcomas, AVL and other RIS revealed high levels of MYC amplification by fluorescence in situ hybridization (FISH) only in secondary angiosarcomas, as opposed to AVL cases or AVL lesions adjacent to RIBA." (PMID 35456944, 2022). "Moreover, incidence of MYC alteration was low in radiation-induced non-breast angiosarcomas, or absent in RIS without angiosarcoma morphology." (PMID 35456944, 2022).
prostate tumors (56 papers, 2004 to 2025). "We found differential and complex ALAN networks associated with the proto-oncogene MYC as prostate tumors develop and become metastatic, between different cancer types, and within cancer subtypes." (PMID 37059746, 2023). "Incorporation of RNA expression data indicated an inverse association between prostate tumor MYC DNA methylation and PRNCR1 expression in tumor tissue." (PMID 33374332, 2020). "Findings suggest that prostate tumor MYC exon 3 hypomethylation is associated with increased aggressiveness." (PMID 33374332, 2020). "As a secondary aim, we sought to explore the potential downstream consequences of prostate tumor MYC DNA methylation by evaluating associations with RNA expression for MYC and other nearby genes and ncRNAs in prostate tumor tissue." (PMID 33374332, 2020). "The directions of our observed associations (i.e., lower MYC methylation in prostate tumor than normal tissue and positive association between MYC methylation and miR-1206 expression) thus also appear to fit with the biology of miR-1206." (PMID 33374332, 2020). "When we incorporated RNA expression data in prostate tumor tissue, we observed significant inverse associations between tumor MYC DNA methylation and expression of the lncRNAs PRNCR1 and CASC11, and a significant positive association with miR-1206 expression." (PMID 33374332, 2020). "To assess the functional implications of the association between PI3K-pathway alteration and MYC amplification in human prostate tumors, we turned to genetically engineered mouse (GEM) models." (PMID 21394210, 2011). "Expression profiling analysis and modeling of transcriptional regulatory networks predicts a functional association between MYC and the prostate tumor suppressor KLF6." (PMID 18190704, 2008). "As a repressor of c-MYC, restoration or pharmacological activation of ABHD5 function may represent a promising strategy for targeting MYC-driven prostate tumors, particularly those with c-MYC overexpression and few actionable mutations." (PMID 41349769, 2025). "We investigated whether MYC DNA methylation at 8q24 (six CpG sites from exon 3 to the 3′ UTR) in prostate tumor was associated with tumor aggressiveness (based on Gleason score, GS), and we incorporated RNA expression data to investigate the function." (PMID 33374332, 2020). "Furthermore, in human prostate tumors, coexpression of c-MYC and PIM1 is associated with higher Gleason grades." (PMID 23565217, 2013). "TUBB4A deletion has been reported to reduce prostate tumor growth and metastasis by inhibiting the activation of NF-κB, cell cycle protein D1, and c-MYC signaling." (PMID 36713586, 2022). "Of note, increased DNA damage but decreased NF-κB, cyclin D1, and c-MYC signaling activation were evident in prostate tumors with a TUBB4A defect." (PMID 35589707, 2022). "The slightly longer survival times of LDH-A KD CT2A and ALTS1C1 tumors compared to NC controls is also consistent with our previous findings with 4T1 breast and MyC-CaP prostate tumors." (PMID 35565435, 2022). "MYC has been reported to stimulate an embryonic stem cell–like expression signature in MYC-driven mouse prostate tumors." (PMID 35912174, 2022). "Here, we have integrated chromatin immunoprecipitation sequencing (ChIP-seq) and whole-transcriptome sequencing to identify novel regulators of metabolism in advanced prostate tumors characterized by elevated MYC activity." (PMID 36181613, 2022). "NKX3-1 deletions by FISH were observed in 17/42 (17.5%) prostate tumors arising in men of ME ancestry, while MYC amplifications were only observed in 1/42 (2.3%)." (PMID 34068856, 2021). "We observed higher accessibility to the promoter region of MYC in Gleason pattern 4 prostate tumours." (PMID 34911933, 2021). "In contrast, the expressions of MYC in metastasis prostate tumors in different cohorts were inconsistent." (PMID 34858826, 2021).
prostate tumors (continued). "To validate this observation, we screened a new cohort of treatment naïve Gleason score 7 prostate tumors for MYC and Ki67 expression by IHC." (PMID 32681068, 2020). "In summary, our analysis of MYC-expressing prostate tumors demonstrates an inverse relationship with MEIS1 expression, which in turn is negatively correlated with HOXB13 expression and AR activity." (PMID 32681068, 2020). "The long non-coding RNA PVT1 within the amplification SCNA identified on 8q24.21 is overexpressed in both AA breast and prostate tumors, and it was found that the overexpression of the MYC oncogene in tumors depends on PVT1 expression." (PMID 32819446, 2020). "MYC is a regulator of cell growth and overexpression of MYC has been observed in the initial stages of prostate tumors." (PMID 28005952, 2016). "Ectopic overexpression of c-MYC/c-Myc is sufficient to immortalize human prostate epithelial cells and has been shown to generate human-like prostate tumors in mice." (PMID 18190704, 2008). "The 8q24 region appears amplified in up to 50% of prostate tumors and c-MYC is thought to be the primary target of these amplifications since it is overexpressed in prostate hyperplasia and neoplasia." (PMID 18190704, 2008). "However, to the best of our knowledge, the current study is the first to demonstrate an epigenetic link between ArA metabolism, uptake, and MYC activity in human prostate tumors." (PMID 36181613, 2022). "We have reported that ArA metabolism and uptake are enriched in MYC-high prostate tumors." (PMID 36181613, 2022). "Here, we showed that miR-32 promotes prostate tumors induced by the expression of oncogenic MYC." (PMID 35228520, 2022). "Our findings indicated lower MYC DNA methylation in prostate tumor compared to paired normal prostate tissue samples for all CpG sites evaluated, suggesting that these may represent somatic alterations in prostate tissue." (PMID 33374332, 2020). "Taking an inclusive approach to combine both datasets, we identified 293 and 7390 differentially expressed genes between MYC-high and MYC-low prostate tumors in the LCM tissue and TCGA PRAD cohorts, respectively that were concordantly regulated in the same direction." (PMID 32681068, 2020). "In summary, focusing on CpG sites from exon 3 to the 3′ UTR of MYC, our results suggested lower MYC DNA methylation in prostate tumor compared to paired normal prostate tissue, and lower exon 3 DNA methylation for more aggressive compared to less aggressive tumors." (PMID 33374332, 2020). "When we evaluated prostate tumor MYC DNA methylation in relation to RNA expression in prostate tumor tissue in the University of Maryland samples, we did not observe a significant association between any of the six CpG sites and MYC expression (data not shown)." (PMID 33374332, 2020). "The expression of ALDH1A1, CCNG2 and MYC genes has been reported in aggressive prostate tumors." (PMID 28938627, 2017). "To characterize the intense stromal remodeling and inflammatory infiltrate surrounding mPIN and prostate tumors in MPAKT/Hi-MYC mice, we performed immunohistochemistry for T-lymphocytes (CD-3), B-lymphocytes (B220) and macrophages (Mac-2) on prostate tissues from mice aged 5-9 weeks." (PMID 21394210, 2011). "Interestingly, prostate tumors from Hi-MYC (n = 5) and MPAKT/Hi-MYC (n = 5) mice all showed reduced TUNEL staining after 14 days of RAD001 treatment compared to prostates from vehicle-treated animals (n = 4–5/genotype)." (PMID 21394210, 2011). "In the current study, we used transcriptome profiling to assess subpopulations of prostate tumors based on differential MYC protein expression and MYC activity, and we similarly compared differentially expressed genes and pathways within the larger prostate TCGA cohort based on MYC activity." (PMID 32681068, 2020). "At 120 mg/kg administered orally, SH-BC-893 reduces nuclear MYC levels in tumors, disrupts PP2A-dependent trafficking and inhibits autochthonous prostate tumor growth by 82%." (PMID 40588551, 2025).
prostate tumors (continued). "In a cohort of 177 laser-capture microdissected foci of prostate tumors, KMT2A expression was positively correlated with MYC activity, AR activity, and HOXB13 expression, but decreased with tumor grade severity." (PMID 36181613, 2022). "At 35 weeks, IHC analysis showed AR+ prostate tumors in all mice, but expressions of Ki67+, c-MYC, p-IKKα/β, and p-p65 were lower in Tubb4a-cKO TRAMP versus WT TRAMP prostate tumors." (PMID 35589707, 2022). "Given the evidence of rs1447295 functionally altering expression of MYC and POU5F1B, its influence on prostate tumor progression and metastasis can be asserted." (PMID 29560112, 2018). "Analyses of tumor datasets show that PTOV1 expression significantly correlated with prostate tumor grade, drug resistance (CCNG2) and self-renewal (ALDH1A1, MYC) markers." (PMID 28938627, 2017). "These analyses reveal that primary prostate tumors show significantly higher expression of PTOV1, CCNG2 and MYC compared to benign tissue (GSE29079), and PTOV1 levels significantly correlate with CCNG2 and MYC mRNA levels." (PMID 28938627, 2017). "In the resultant MPAKT/Hi-MYC model, AKT1 and MYC are expressed together in the prostate, recapitulating the co-incidence of the genetic lesions in human prostate tumor samples." (PMID 21394210, 2011). "In fact, we observed significant correlation between MYC and PVT1 expression, r2 = 0.54 (p = 0.021 in 18 prostate tumours) and r2 = 0.34 (p = 0.0073 in 59 normal prostates)." (PMID 21814516, 2011). "The combined genomic and expression profiling analysis described in this study suggested an upregulation of FASN, BARK1, MYC, PP1α, and NM23-H1 expression and a downregulation of PP2A expression in prostate tumours." (PMID 17146477, 2007). "Given that PPP2R1A and these importins are ubiquitously expressed and that JUN, YAP, MYC, and NF-κB drive many different types of cancer, sphingosine-like drugs should be effective across cancer classes, not just against prostate tumors." (PMID 40588551, 2025).